FAM53A (family with sequence similarity 53 member A)
Description:
May play an important role in neural development; the dorsomedial roof of the third ventricle.
Synonyms: DNTNP
Tractability: Antibody: the Human Protein Atlas places it where antibodies can reach.
Gene: Protein-coding gene on chromosome 4 (1,617,915 to 1,684,313, reverse strand). Ensembl gene ENSG00000174137.
Subcellular location: Nucleus
Subcellular location (Human Protein Atlas): Nucleoplasm; Plasma membrane
Gene Ontology:
Biological process: protein import into nucleus
Cellular component: nucleus
Genetic constraint (gnomAD): Loss-of-function variants: 28 observed, 21.22 expected, observed/expected ratio (o/e) 1.32, 90% interval 0.98 to 1.78. The synonymous counts are far from expectation, so gnomAD's model fits this gene poorly and the ratio says little. Missense variants: 650 observed, 504.95 expected, observed/expected ratio (o/e) 1.29, 90% interval 1.21 to 1.37. Synonymous variants: 290 observed, 218.39 expected, observed/expected ratio (o/e) 1.33, 90% interval 1.21 to 1.46.
Homologues: Orthologues: chimpanzee FAM53A (96% identical), macaque FAM53A (88% identical), rat Fam53a (67% identical), mouse Fam53a (67% identical), dog FAM53A (57% identical), pig FAM53A (53% identical), guinea pig FAM53A (51% identical), tropical clawed frog fam53a (51% identical). Paralogues in human: FAM53C (29% identical), FAM53B (26% identical).
Diseases named in the same sentence as FAM53A in open-access papers:
FAM53A is named in the same sentence as 7 diseases in open-access papers, as found by Europe PMC text mining. Sharing a sentence is not in itself a finding about the gene and the disease. The quoted sentences say what the papers report.
breast carcinoma (2 papers, 2017 to 2019). "To investigate the association between FAM53A expression and clinicopathological features of breast cancer, we selected 199 breast cancer tissues for immunohistochemical staining." (PMID 31799197, 2019). "We then altered FAM53A expression in two breast cancer cell lines to explore its effects on the cells and gain mechanistic insight into how FAM53A affects cancer." (PMID 31799197, 2019). "The use of PD98059 to antagonize ERK activation after FAM53A overexpression or depletion indicated that FAM53A affects breast cancer proliferation, migration, and invasion via the MEK/ERK signaling pathway." (PMID 31799197, 2019). "In this study, we examined the expression and localization of FAM53A in breast cancer tissues and cell lines." (PMID 31799197, 2019). "The role of FAM53A in breast cancer is unclear, and its relevance to the clinical pathology of breast cancer has not been reported." (PMID 31799197, 2019). "We examined the localization of FAM53A in the breast cancer cell lines MCF-7, T47D, MDA-MB-231, and BT-549 and the non-malignant human mammary epithelial cell line MCF-10A by immunofluorescence and observed its presence in the cytoplasm and nucleus." (PMID 31799197, 2019). "RNAi-based depletion of a predicted regulatory target gene, FAM53A, indicated that this gene can modulate doxorubicin sensitivity in breast cancer cell lines." (PMID 28179588, 2017). "In addition, FAM53A may affect the migration and invasion of breast cancer cells by regulating the expression of RhoA, RhoB, RhoC, ROCK1, and MMP9." (PMID 31799197, 2019). "The MEK inhibitor PD98059 reduced the biological effects of FAM53A knockdown in MCF-7 cells and FAM53A overexpression in MDA-MB-231 cells, suggesting that FAM53A affects breast cancer through the MEK-ERK pathway." (PMID 31799197, 2019).
osteoarthritis (2 papers, 2021 to 2022). A noninflammatory degenerative joint disease occurring chiefly in older persons, characterized by degeneration of the articular cartilage, hypertrophy of bone at the margins and changes in the synovial membrane. "For seven genes (ALDH1A2, CHMP1A, CRADD, FAM53A, LTBP1, RPP25, and TGFA), we found evidence that GWAS signals for osteoarthritis colocalize with mQTLs in these genes and are additionally associated with gene expression levels in the same tissue." (PMID 35679866, 2022). "We found strong evidence for co-localisation of five osteoarthritis signals with cartilage molQTLs for ALDH1A2, NPC1, SMAD3, FAM53A and SLC44A2." (PMID 33637762, 2021). "We found such an eQTL effect below nominal significance levels for five genes in low-grade osteoarthritis cartilage (ALDH1A2, CHMP1A, FAM53A, RPP25, and TGFA), two genes in high-grade osteoarthritis cartilage (FAM53A and LTBP1), and one gene in synovium (CRADD)." (PMID 35679866, 2022).
bladder cancer (1 paper, 2025). "Higher whole blood expression of FAM53A, located on 4p16.3, was associated with higher bladder cancer risk." (PMID 39789109, 2025). "Higher whole blood expression of FAM53A and PPP1R2 was associated with higher odds of bladder cancer, while higher expression of SLC39A3 and ZNF737 was associated with lower odds of bladder cancer." (PMID 39789109, 2025). "A total of four genes (SLC39A3 on 19p13.3, ZNF737 on 19p12, FAM53A on 4p16.3, and PPP1R2 on 3q29) were identified to be associated with bladder cancer risk with FDR < 0.05." (PMID 39789109, 2025). "TWAS identified four genes for which expression levels were associated with bladder cancer risk: SLC39A3 (OR = 0.91, CI = 0.87–0.95, FDR = 0.015), ZNF737 (OR = 0.91, CI = 0.88–0.95, FDR = 0.016), FAM53A (OR = 1.09, CI = 1.05–1.14, FDR = 0.022), and PPP1R2 (OR = 1.09, CI = 1.05–1.13, FDR = 0.049)." (PMID 39789109, 2025).
invasive breast carcinoma (1 paper, 2019). A carcinoma that infiltrates the breast parenchyma.
ovarian carcinoma (1 paper, 2020). A malignant neoplasm originating from the surface ovarian epithelium. "It has been reported that CYP26A1, MTRNR2L1, ELOA, and FAM53A were all related with ovarian carcinomas, and CYP26A1 may acts as a meiosis-inhibiting factor and related with the gonadal retinoic acid-degradation." (PMID 32425983, 2020).
cancer (1 paper, 2019). A tumor composed of atypical neoplastic, often pleomorphic cells that invade other tissues. "While FAM53A has yet to be directly linked to tumorigenesis, studies have shown that members of the FAM53 protein family bind to transcriptional regulators that regulate cell proliferation, suggesting potential effects on cancer development." (PMID 31799197, 2019). "Our understanding of the role of FAM53A in cancer tumorigenesis and progression is limited." (PMID 31799197, 2019).
FAM53A also shares sentences with these, for which no sentence is quoted: tumor suppressor (1 paper).